EZH2 (enhancer of zeste 2 polycomb repressive complex 2 subunit)
Diseases named in the same sentence as EZH2 in open-access papers (continued):
Sharing a sentence is not in itself a finding about the gene and the disease.
melanoma (continued). "In patients with BRAF V600E-mutated melanoma, the individual EZH2 gain status should be tested first, and cotreatment with BRAF and EZH2 inhibitors can be applied to patients containing EZH2 gain and BRAF V600E mutation simultaneously to enhance the anticancer effects." (PMID 29202777, 2017). "EZH2 gain-of-function mutations often occur concurrently with the BRAF V600E mutation in melanoma." (PMID 29202777, 2017). "Taken together, our findings indicated that EZH2 gain may be an adverse prognostic biomarker in BRAF V600E-mutated melanoma." (PMID 29202777, 2017). "Among the 138 patients with BRAF V600E-mutated melanoma, 40 cases (29.0%) showed EZH2 gain." (PMID 29202777, 2017). "Coexistence of BRAF V600E mutation and EZH2 gain is rather prevalent in melanoma." (PMID 29202777, 2017). "EZH2 has previously been implicated in driving melanoma cell migration and invasion." (PMID 28119061, 2017). "Correlation of EZH2 gain to clinicopathologic features of BRAF V600E mutated melanomas." (PMID 29202777, 2017). "However, recent studies have identified acquired EZH2 mutations in lymphoma cancer, myeloid neoplasms and melanoma that are associated with the development of malignancy by regulating the expression of the complex of PcG genes to determine cell fate." (PMID 27092879, 2016). "A number of histone methyltransferases are implicated as having a role in melanoma, especially enhancer of zeste homolog 2 (EZH2)—the catalytic subunit of the Polycomb Repressive Complex 2 (PRC2) complex which represses transcription by adding the H3K27me3 mark." (PMID 26426052, 2015). "Activating mutations in EZH2 occur in 3% of melanoma, where it functions as a driver of melanoma progression, and its expression may be upregulated in a further cohort of melanoma." (PMID 26426052, 2015). "Furthermore, miR-31 overexpression resulted in down-regulation of EZH2 and a de-repression of its target gene rap1GAP; increased expression of EZH2 was associated with melanoma progression and overall patient survival." (PMID 22948084, 2012). "Our results are in line with studies in several other tumor forms, including malignant melanoma and cancers of the breast, prostate, endometrium, stomach, and liver, where increased EZH2 expression has been linked to more aggressive tumor behaviour and poor prognosis." (PMID 20920340, 2010). "Interestingly, ARID1A mutations were detected more frequently on the head and extremities, compared to the trunk, and ARID1A-truncating mutations were associated with later stages of melanoma progression, correlating with an increase in the expression of an EZH2 transcriptional program." (PMID 35323214, 2022). "Treatment of these cells with different doses of the chemotherapy drugs (BRAF inhibitor), dabrafenib or vemurafenib, used in melanoma treatment revealed that USP7- or EZH2-deficient cells were more sensitive to chemotherapeutics, which could be partially rescued by FOXO1 knockdown." (PMID 33849069, 2021). "Similarly, subsequent studies have widely implicated the overexpression of EZH2 in the development of various solid malignancies including those of prostate, breast, bladder and pancreatic cancers, hepatocellular carcinoma, and melanoma among others." (PMID 32448308, 2020). "Hierarchical clustering revealed strong EZH2 and/or H3K27me3 enrichment at multiple TDGs, particularly in iPSCs (EZH2) and fibroblast or melanoma cells (H3K27me3)." (PMID 41147659, 2026). "Histone H3 lysine 27 trimethylation, which was downregulated by Enhancer of Zeste Homolog 2 (EZH2), has been identified as a key role in the invasive/mesenchymal regulators of NRAS mutation melanoma." (PMID 41492362, 2026). "Here, we identify the histone methyltransferase EZH2 as a key regulator of HS biosynthesis in melanoma." (PMID 41648528, 2026).
melanoma (continued). "Pharmacological inhibitors of EZH2, including tazemetostat, have shown promise in preclinical melanoma models by restoring antigen presentation, enhancing CD8+ T-cell infiltration, and reversing transcriptional programs associated with immune resistance." (PMID 42220432, 2026). "Recent multi-omic studies have highlighted the importance of EZH2 in regulating melanoma plasticity, immune modulation, and metabolic reprogramming." (PMID 42220432, 2026). "Instead, treatment with both compounds-most prominently SG-8-was associated with reduced phosphorylation levels of EZH2 (Ser21) and its upstream regulator Akt (Ser473), suggesting that modulation of the Akt-EZH2 signaling axis may at least partially contribute to their anti-melanoma activity." (PMID 41898517, 2026). "Our experiments revealed that melanoma-derived IκBζ interacts with EZH2 and HDAC3, facilitating their recruitment to the respective promoter regions, resulting in silencing of gene expression." (PMID 40562773, 2025). "Through its effects on histone modifications, EZH2 regulates gene expression that directly affects immune cell recognition and alters the overall immunogenicity of melanoma cells, allowing the tumor to evade immune surveillance." (PMID 40872475, 2025). "EZH2 inhibitors, including specific small molecules, can reduce cell growth and melanoma metastases, making EZH2 a potential therapeutic target." (PMID 40427015, 2025). "The results revealed that melanoma cells exhibited substantial expression of critical stemness-associated genes, namely HIF1A, EPAS1, TWIST1 and EZH2." (PMID 41383633, 2025). "Functional studies indicated that inhibiting EZH2 with GSK503 reversed several resistance mechanisms in melanomas, leading to improved synergy between different immunotherapies and enhanced antitumor cytotoxicity." (PMID 39946195, 2025). "They then combined an EZH2 inhibitor with diABZI to increase the STING expression in melanoma and successfully reduce the tumor growth by eliciting numerous antitumor immune responses." (PMID 40333245, 2025). "FOXC2-AS1 stimulates the proliferation of melanoma cells via silencing p15, a tumour-suppressor gene that prevents cell cycle progression from the G1 phase to S phase through recruiting EZH2." (PMID 41463281, 2025). "miR‐26a is downregulated in melanoma, where it normally acts as a tumour suppressor by targeting EZH2, an oncogenic histone methyltransferase." (PMID 39823244, 2025). "Clinical trials have not yet demonstrated the efficacy of EZH2 inhibition in patients with EZH2-mutant melanoma." (PMID 39984702, 2025). "In melanoma, EZH2 overexpression contributes to excessive trimethylation of H3K27 on tumor suppressor genes and has been proposed to be a mechanism of tumor progression and metastasis." (PMID 39984702, 2025). "Inhibiting SCD1 re-establishes proper EZH2-mediated transcriptional repression, thereby restoring epigenetic control and sensitizing melanoma cells to EZH2-targeted therapies." (PMID 40573249, 2025). "EZH2 overexpression occurs frequently in different types of cancer including melanoma while its activity leads to gene silencing through DNA methylation of tumor‐suppressor elements." (PMID 40959208, 2025). "The miR‐26a/EZH2 axis plays a significant role in maintaining cell cycle checkpoints, and its disruption is a key event in melanoma's pathogenesis and aggressiveness." (PMID 39823244, 2025). "Our study investigated EZH2 copy number variation in 547 melanoma patients, revealing EZH2 copy number gain in MM specifically." (PMID 39518098, 2024). "Through analyzing the pan-cancer copy number variations of the EZH2 gene using the cBioPortal database, we identified a high frequency of EZH2 gene copy number amplification in melanoma." (PMID 39518098, 2024). "For melanomas, the depletion of EZH2 in established melanoma stopped the emergence of further skin tumors." (PMID 39768352, 2024).
melanoma (continued). "Transmission electron microscopy (TEM) analysis revealed mitochondrial shrinkage with elevated membrane density, a typical morphologic feature of ferroptosis, in EZH2-depleted melanoma cells." (PMID 39518098, 2024). "To further evaluate the impact of this novel predictive biomarker identified by KL-Relevance approach, we then assessed drug responses in four melanoma cell lines under varying EZH2 and BRAF statuses treated with PLX-4720." (PMID 39304771, 2024). "Previous studies have shown that EZH2 is crucial in melanoma progression and metastasis, yet its function in MM remains elusive." (PMID 39518098, 2024). "Early evidence comes from solid tumor studies where EZH2 overexpression has been observed in multiple cancers, including prostate cancer, breast cancer, bladder cancer, endometrial cancer, and melanoma." (PMID 38339397, 2024). "As reported, UHRF1-mediated ubiquitination regulates EZH2 proteins to induce differentiation phenotypes in melanoma." (PMID 39709438, 2024). "During our genome sequencing to search for melanoma driver genes, we previously noted EZH2 copy number amplification." (PMID 39518098, 2024). "Previous studies on high PRAME expression in SS, and reports on its interaction with EZH2 and RARs in melanoma and AML prompted us to analyze the expression of PRAME, EZH2, and the RAR genes in different soft-tissue sarcomas (STS)." (PMID 39550391, 2024). "Consistent with this, paracrine Cxcl9 and Cxcl10 was significantly upregulated after the introduction of K510A mutant EZH2 into melanoma cells with endogenous EZH2 silencing." (PMID 38461299, 2024). "A decrease in the EZH2 protein abundance in pigmented melanoma cells alters the phenotypes of LPCs to those of HPCs and thereby suppresses tumorigenic proliferation." (PMID 39394462, 2024). "To investigate the effect of EZH2 knockdown on cell death mechanisms, we exposed EZH2-depleted melanoma cells to various cell death inducers." (PMID 39518098, 2024). "In another study, immunohistochemical staining showed that in melanoma cells, the levels of EZH2 and H3K27me3 are increased in cells at the invasive front compared to cells found in the center of the tumor." (PMID 39409910, 2024). "EZH2 point mutation experiments indicated that the trimethylation of H3K27 was significantly reduced after exogenously expressing an EZH2 K510A mutant in melanoma cell with stable EZH2 silencing." (PMID 38461299, 2024). "Among 547 melanoma patients, MM showed higher EZH2 gain frequency, significant only in the primary site (64/164,39.0%, p < 0.001)." (PMID 39518098, 2024). "We discovered that the enhancer of zeste homolog 2 (EZH2) plays a crucial role in promoting the growth of mucosal melanoma cells and contributes to their resistance to a type of cell death known as ferroptosis." (PMID 39518098, 2024). "In melanoma, the dysregulation of histone-modifying enzymes, such as histone methyltransferases (e.g., EZH2) and histone deacetylases (e.g., HDAC), has been observed." (PMID 39200315, 2024). "To elucidate EZH2’s role in mucosal melanoma progression, we also performed RNA sequencing (RNA-seq) analysis, revealing 1182 genes were upregulated and 1350 genes downregulated after EZH2 depletion." (PMID 39518098, 2024). "Targeting the interaction between lncRNAs and EZH2 has shown potential in slowing down melanoma progression." (PMID 39200315, 2024). "Methylated-EZH2 subsequently activated the trimethylation of H3K27 to inhibit the transcription of ISGs in melanoma." (PMID 38461299, 2024). "Specific inhibitors of EZH2 activity induce ciliogenesis and cilia-dependent tumor growth suppression and are, thus, considered as a strategy for treating melanoma." (PMID 37510333, 2023). "The TF NFATc2 expressed in MITFlow melanoma cells was linked to an epithelial–mesenchymal transition (EMT)-like program of melanoma cells associated with myc, FOX1 and EZH2 expression." (PMID 37347257, 2023).
melanoma (continued). "In our previous work, we elaborated that EZH2 is expressed even more strongly in melanoma cells resistant to vemurafenib than in cells that respond to it." (PMID 36768289, 2023). "Accordingly, melanoma cell viability and invasiveness were promoted by overexpression of EZH2-K381R in UBE2L6-overexpressing cells." (PMID 36906655, 2023). "Increased levels of EZH2 and H3K27me3, observed specifically in melanoma cell lines resistant to vemurafenib or its analog PLX4720, have triggered silencing of melanoma tumor suppressor phosphatase and tensin homolog (PTEN)." (PMID 37325482, 2023). "In previous reports, EZH2 was already shown to contribute to melanoma progression by silencing distinct tumor suppressor genes, which results in aggressive tumor subgroups of cutaneous melanoma with higher proliferation rates and increased metastasis." (PMID 36768289, 2023). "This review demonstrates that several lncRNAs contribute to melanoma progression via direct interaction with EZH2." (PMID 37325482, 2023). "We found that the addition of an EZH2 inhibitor to vemurafenib improved the response of melanoma cells resistant to BRAFi with regard to decreased viability, cell-cycle arrest and increased apoptosis." (PMID 36768289, 2023). "The function of EZH2, particularly in BRAF-mutated melanoma and in the emergence of resistance to targeted therapies, was incompletely understood." (PMID 36768289, 2023). "Our data now provide the first evidence that the whole PLK1 pathway is strongly downregulated after the inhibition of BRAF and EZH2 in resistant melanoma cells." (PMID 36768289, 2023). "It has been demonstrated also that therapeutic strategies targeting EZH2 or its downstream targets, such as the ciliary-related oncogene PLK1, in combination with BRAF inhibitors are potential novel therapeutic options in melanomas with BRAF mutations." (PMID 37510333, 2023). "The study also highlighted the possibility of PVT1 binding to enhancer of zeste homolog 2 (eZH2) in melanoma cells and regulating the expression of microrna-200 (mir-200c), proposing another pathway involved in cell proliferation." (PMID 37629553, 2023). "To investigate this, we evaluated EZH2 mRNA and EZH2 protein levels, as well as a marker of EZH2’s methyltransferase activity, H3K27me3, in HPCs and LPCs from 28:F3:B4, B16-F10 and C006-M1 pigmented melanoma cells." (PMID 36906655, 2023). "We identified melanin pigment content as a major source of cellular heterogeneity in melanoma and compared RNAseq data from high-pigmented (HPCs) and low-pigmented melanoma cells (LPCs), suggesting EZH2 as a master regulator of these states." (PMID 36906655, 2023). "It has also been shown that EZH2 enzymatic inhibitors have better activity against EZH2 mutant melanoma cells than wild type cells." (PMID 36906655, 2023). "As increasing EZH2 protein expression was observed from benign nevi to metastatic melanoma and as melanoma patient survival was inversely correlated with EZH2 expression, we sought to extend these findings." (PMID 36906655, 2023). "The possibility of blocking lncRNAs-EZH2 interaction in melanoma as a novel therapeutic option and plausible controversies and drawbacks of this approach are also briefly discussed." (PMID 37325482, 2023). "To investigate EZH2 in melanoma cell pigmentation, we suppressed EZH2 protein and/or EZH2 activity in pigmented melanoma cells." (PMID 36906655, 2023). "Overexpression of EZH2 has been observed in breast cancer, bladder cancer, prostate cancer and melanoma." (PMID 37427115, 2023). "This miRNA has been found to suppress the expression of cMYC, Y-box binding protein 1 (YB1), MITF and EZH2 in melanoma." (PMID 37325482, 2023). "Pleiotropic and diverse roles of EZH2 prompted scientists worldwide to explore this methyltransferase as a promising target in the treatment of melanoma patients." (PMID 37325482, 2023).
melanoma (continued). "While in this review we focus on lncRNAs-EZH2 interaction, mainly in melanoma, diverse approaches to modulate the levels of specific lncRNAs or attempts to decrease EZH2 activity in melanoma have been described in other review papers." (PMID 37325482, 2023). "Previous studies implicated genes involved in melanin biosynthesis and melanocytic differentiation as key targets of EZH2-directed histone methylation, leading to altered pigmentation and differentiation phenotypes in melanoma cells." (PMID 36906655, 2023). "In melanoma, the EZH2 gain in benign melanocytic lesions has been shown to promote the loss of PCs, to enhance pro-tumorigenic Wnt/β-catenin signaling, and to drive metastatic processes." (PMID 37510333, 2023). "We have previously shown that the BRAFV600E signaling pathway mediates the expression of EZH2, an epigenetic regulator related to melanoma progression and worse overall survival." (PMID 36768289, 2023). "Invasive melanoma cells have lower pigment levels compared with non-invasive cells and Ezh2 promotes the low-pigment phenotype in vivo by suppressing Oca2, among other targets." (PMID 36906655, 2023). "Although we found that DZNep reduces EZH2 in melanoma by inducing UBE2L6 expression, its short half-life and broad effects on ubiquitination hinder clinical application." (PMID 36906655, 2023). "5’-Aza induced an 80% decline in UBE2L6 CpG island methylation spanning −582 to −378 from the transcription start site, increased UBE2L6, reduced EZH2, and impaired viability in multiple melanoma cell lines." (PMID 36906655, 2023). "Furthermore, even in EZH2 wild-type melanomas, the expression of EZH2 is increased in approximately 30% of BRAFV600E mutated melanomas, suggesting that there may be a greater dependency on EZH2 activity in a sizable number of patients with BRAFV600E-mutated melanomas." (PMID 37370834, 2023). "This review summarizes current knowledge regarding the involvement of lncRNAs in EZH2-mediated gene silencing in melanoma." (PMID 37325482, 2023). "We found that combined treatment with inhibitors against BRAF and EZH2 indeed showed synergistic effects against cancer cells and improved the response of melanoma cells resistant to vemurafenib." (PMID 36768289, 2023). "EZH2 protein was found to be upregulated in LPCs and inversely correlated with melanin deposition in pigmented patient melanomas." (PMID 36906655, 2023). "Targeting DNA methylation and EZH2 activity can overcome melanoma resistance to immunotherapy via modulating PD-L1 expression and/or T cell infiltration." (PMID 37427115, 2023). "Here, we report UBE2L6 as an E2 ubiquitin-conjugating enzyme for EZH2 that regulates EZH2 abundance in melanoma cells." (PMID 36906655, 2023). "With regard to melanocytic tumors, the expression of EZH2 is higher in malignant melanoma entities than in benign nevi." (PMID 36768289, 2023). "Melanoma cases were found to contain homozygous and heterozygous deletions in EZH2, SUZ12, and EED, and cases with these alterations frequently had decreased mRNA levels of the deleted gene." (PMID 35223844, 2022). "EZH2′s repressive epigenetic mark H3K27me3 is highly expressed in metastatic melanomas in comparison to primary melanomas." (PMID 36230787, 2022). "One exception is melanoma, where levels of both H3K27me3 and EZH2 were found increased, and silenced transcription of the tumor suppressor genes E-cadherin and RUNX3." (PMID 36371348, 2022). "Most recently NFIB has been shown to mediate a highly invasive and migratory phenotype in melanoma, where it directly promotes EZH2 expression, also leading to changes in the chromatin state of tumor cells to facilitate this aggressive behavior." (PMID 35655758, 2022). "To elucidate the role of PRC2 in melanoma, we overexpressed EZH2, EZH2-Y641F, EZH2-Y641N, H3.3, and H3.3K27M using miniCoopR." (PMID 35223844, 2022).